SLC16A1-AS1 (SLC16A1 antisense RNA 1)
Synonyms: ENST00000421157.1; LINC01357; HP08777
Gene: Long non-coding RNA gene on chromosome 1 (112,849,483 to 113,047,059, forward strand). Ensembl gene ENSG00000226419.
Diseases named in the same sentence as SLC16A1-AS1 in open-access papers:
SLC16A1-AS1 is named in the same sentence as 1 disease in open-access papers, as found by Europe PMC text mining. Sharing a sentence is not in itself a finding about the gene and the disease.
SLC16A1-AS1 shares sentences with these, for which no sentence is quoted: glioblastoma (1 paper).